OR2F2 (olfactory receptor family 2 subfamily F member 2)
Description:
Odorant receptor.
Synonyms: OR7-1
Tractability: Antibody: UniProt places it where antibodies can reach, with medium confidence; UniProt predicts a signal peptide or a membrane-spanning region; its Gene Ontology location is reachable by antibodies, with medium confidence. PROTAC: ubiquitination databases record sites on it.
Gene: Protein-coding gene on chromosome 7 (143,935,233 to 143,936,186, forward strand). Ensembl gene ENSG00000221910.
Subcellular location: Cell membrane
Pathways (Reactome):
Sensory Perception: Expression and translocation of olfactory receptors
Gene Ontology:
Molecular function: olfactory receptor activity; G protein-coupled receptor activity
Biological process: detection of chemical stimulus involved in sensory perception of smell; G protein-coupled receptor signaling pathway
Cellular component: plasma membrane; membrane
Genetic constraint (gnomAD): Loss-of-function variants: 1 observed, 1.57 expected, observed/expected ratio (o/e) 0.64, 90% interval 0.2 to 1.83. That is too few expected variants to judge how well the gene tolerates losing a copy. Missense variants: 375 observed, 390.72 expected, observed/expected ratio (o/e) 0.96, 90% interval 0.88 to 1.04. Synonymous variants: 161 observed, 163.06 expected, observed/expected ratio (o/e) 0.99, 90% interval 0.87 to 1.12.
Homologues: Orthologues: chimpanzee OR2F2 (97% identical), dog OR2F1D (84% identical), dog OR2F1 (84% identical), mouse Or2f1 (84% identical), rat Or2f1 (84% identical). Paralogues in human: OR2F1 (90% identical), OR2D3 (52% identical), OR2D2 (49% identical), OR2K2 (48% identical), OR2G6 (48% identical), OR13D1 (47% identical), OR13C8 (47% identical), OR5V1 (46% identical), OR13C4 (46% identical), OR2S2 (46% identical), OR10A3 (46% identical), OR13C9 (46% identical), and 80 more.
Diseases named in the same sentence as OR2F2 in open-access papers:
OR2F2 is named in the same sentence as 1 disease in open-access papers, as found by Europe PMC text mining. Sharing a sentence is not in itself a finding about the gene and the disease.
OR2F2 shares sentences with these, for which no sentence is quoted: depression (1 paper).